CFAP299 (cilia and flagella associated protein 299)
Description:
May be involved in spermatogenesis.
Synonyms: C4orf22
Tractability: Small molecule: a structure with a bound ligand is known. Antibody: the Human Protein Atlas places it where antibodies can reach.
Gene: Protein-coding gene on chromosome 4 (80,335,730 to 80,963,750, forward strand). Ensembl gene ENSG00000197826.
Subcellular location: Cytoplasm; Nucleus
Subcellular location (Human Protein Atlas): Cytosol; Plasma membrane
Gene Ontology:
Molecular function: protein binding
Cellular component: cytoplasm; nucleus
Genetic constraint (gnomAD): Loss-of-function variants: 10 observed, 12.48 expected, observed/expected ratio (o/e) 0.8, 90% interval 0.49 to 1.36. The upper end of that interval is the gene's LOEUF score, 1.36, which puts it in group 5 of 6, group 1 being the genes least tolerant of losing a copy. Missense variants: 123 observed, 129.18 expected, observed/expected ratio (o/e) 0.95, 90% interval 0.82 to 1.11. Synonymous variants: 52 observed, 44.44 expected, observed/expected ratio (o/e) 1.17, 90% interval 0.94 to 1.47.
Homologues: Orthologues: chimpanzee CFAP299 (98% identical), macaque CFAP299 (95% identical), dog CFAP299 (86% identical), rabbit CFAP299 (85% identical), rat Cfap299 (85% identical), mouse Cfap299 (85% identical), pig CFAP299 (84% identical), guinea pig CFAP299 (82% identical), tropical clawed frog cfap299 (71% identical), zebrafish cfap299 (60% identical), Drosophila melanogaster CG8138 (30% identical), Drosophila melanogaster CG14017 (29% identical), and 2 more.
Diseases named in the same sentence as CFAP299 in open-access papers:
CFAP299 is named in the same sentence as 3 diseases in open-access papers, as found by Europe PMC text mining. Sharing a sentence is not in itself a finding about the gene and the disease.
CFAP299 shares sentences with these, for which no sentence is quoted: cancer (1 paper); developmental delay (1); Hypertension (1).